CCND1 (cyclin D1)
Diseases named in the same sentence as CCND1 in open-access papers (continued):
Sharing a sentence is not in itself a finding about the gene and the disease.
cancer (continued). "The significant down-regulation of cyclin D1 level in all three CCA cell lines exposing to salirasib alone suggested that salirasib could affect cyclin D1 expression in CCA cells as reported in other cancer cells." (PMID 34837922, 2021). "Therefore, it is likely that the reduced cell growth and suppressed cancer progression observed in the presence of miR‐194 are a result of downregulated CCND1 levels, although additional targets of miR‐194 identified through RNA sequencing have not been ruled out." (PMID 34081843, 2021). "Finally, a multivariable analysis using Cox proportional-hazards regression demonstrated that CCND1 amplification was significantly associated with a shorter median OS [HR 1.60 (95% CI 1.16–2.21), P = 0.0040], with adjustment for TMB, cancer type, age, drug class of ICI, and the year of ICI start." (PMID 32903763, 2020). "The role of Cyclin D1 in cancer initiation and progression appears complex and multifaceted, indicating that nowadays further investigations are needed for a more exhaustive comprehension of the therapeutic intervention targeting Cyclin D1-dependent mechanisms." (PMID 33317149, 2020). "Therefore, alternative strategy is needed to block Cyclin D1 activity in cancer." (PMID 33139730, 2020). "The toxicity of AG-1 in cancer cells appears to be due to its ability to shift cellular redox status to a more oxidized environment that is accompanied with a significant decrease in cyclin D1 protein expression and increase in the percentage of cells in the G1-phase of the cell cycle." (PMID 31991904, 2020). "Finally, in cancer, amplification of CCND1 is among the most common genetic events (condition 6)." (PMID 33166394, 2020). "Therefore, our results indicated that reduced expression of CD9 and CD81 in HCC may activate JNK signaling pathway, which promotes cancer cell proliferation via regulating the downstream genes such as Cyclin D1 and Bcl-2." (PMID 32350244, 2020). "Indeed, the CCND1 gene is amplified in a variety of human cancers." (PMID 32429232, 2020). "These researches indicated that cyclin D1 may play different roles in the prognosis of cancer." (PMID 32697404, 2020). "Additionally, KLF6-SV1 silencing could reduce activity of the PI3K-AKT pathway, which is a key pathway that is upregulated in human cancers 5, as well as reduce the expression of Cyclin D1." (PMID 31632477, 2019). "Moreover, the PI3K/AKT pathway is closely related to CCND1 in several cancers, including CRC." (PMID 31196027, 2019). "Notably, PIN1 has been found to interact with cyclin D1 in cancer cells." (PMID 32010690, 2019). "In conclusion, present meta-analysis showed that CCND1 SNP (rs9344) may not serve as a risk factor for overall cancer susceptibility in Indian population." (PMID 30361291, 2018). "Cyclin D1 is an oncoprotein that plays a key role in the development of all cancer cells and leads to increased cell proliferation, which gives neoplastic cells a growth advantage and may also favor the occurrence of additional genetic lesions with potential oncogenic effects." (PMID 29448931, 2018). "MiR-195 could suppress the development of cancers by targeting CCND1." (PMID 29298665, 2018). "Interestingly, PIN1 expression is positively correlated with cyclin D1 expression in these cancers." (PMID 30534074, 2018). "The direct involvement of CCND1 in human cancer cell migration/invasion is virtually unknown." (PMID 30459815, 2018). "However, the spectrum of CCND1 mutations across human cancers has not been systematically investigated." (PMID 29969496, 2018). "In addition, resibufogenin could degrade cyclin D1 to induce G1-phase arrested in human malignant cancer cells and have a prevention of oxidative stress in a rat model of human preeclampsia." (PMID 30108651, 2018).
cancer (continued). "To confirm this hypothesis, we first detected SLC7A11 and cyclin D1 levels in cancer tissue." (PMID 29348845, 2017). "In addition to PIM1, miR-33a has been also shown to directly target a variety of genes associated with cancer progression including several genes associated with cell cycle regulation such as CDK6 (cyclin-dependent kinase 6) and CCND1 (cyclin D1), which are directly targeted by miR-33a." (PMID 28947967, 2017). "Therefore, by maintaining stemness and the proliferation of CSCs in HCC tumors, cyclin D1-Smads signaling may be a critical contributor to clinical cancer poor prognosis and conventional treatment failure." (PMID 28415588, 2017). "Thus, overexpression of CDK4 and cyclin D1 is invariably correlated with cancer progression." (PMID 29183322, 2017). "Therefore, ANT2 has potential as a target against cyclin D1-overexpressing cancers." (PMID 28368390, 2017). "Thus, the regulation of cyclin D1 protein level may be useful for the prevention and treatment of cancer." (PMID 28870200, 2017). "Therefore, decreasing the cyclin D1 expression level might be considered as a strategy in cancer therapy." (PMID 27976692, 2016). "Our discovery that obatoclax targets cyclin D1 for degradation provides a novel insight into the anticancer mechanisms of obatoclax, but also identifies a potential application of obatoclax for the therapeutic ablation of cyclin D1 to treat the cancers addicted to aberrant cyclin D1 overexpression." (PMID 28035994, 2016). "Interestingly, cyclin D1 is frequently over-expressed in human malignant tumors." (PMID 26121043, 2015). "Therefore, resibufogenin might be worth developing as a possible treatment for the malignant tumors with cyclin D1 over-expression." (PMID 26121043, 2015). "In addition to cyclin D1, rapalogs induce GSK3-dependent degradation of other oncogenic proteins such as c-Myc and Mcl-1; these effects should be tightly associated with rapalogs’ cancer therapeutic efficacies." (PMID 25797247, 2015). "Importantly, cyclin D1 expression is often deregulated in cancer cells." (PMID 26273627, 2015). "We firstly performed a hospital-based case-control study involving 165 NPC cases and 191 cancer-free controls in central-south China, and then conducted a meta-analysis with six case-control studies to evaluate the association between NPC risk and CCND1 G870A polymorphism." (PMID 25409185, 2014). "Accordingly, inhibition of cyclin D1 may be an innovative strategy for cancer treatment." (PMID 24618206, 2014). "Importantly, CCND1 expression is often deregulated in cancer cells." (PMID 23983695, 2013). "This innovative finding provides new insight into the regulation of OCT4 on CCND1 expression through a previously unidentified mechanism and indicates a variety of novel biological and prognostic markers, as well as potential therapeutic targets, for cancer diagnosis and treatment." (PMID 23433354, 2013). "In addition, z-Gug could inhibit the protein expression of β-Catenin as well as the protein levels of C-myc, Cyclin D1 and survivin in both cancer cells." (PMID 23914993, 2013). "Mirk/Dyrk1B contributes to G0 arrest by destabilization of cyclin D1 and stabilization of p27kip1 to maintain the viability of quiescent human cancer cells, and it could be negatively regulated by mitogenic-activated protein kinase (MAPK)/extracellular signal-regulated kinase (ERK) signaling." (PMID 23311607, 2013). "Therefore, the importance of cyclin D1 in cancer makes it an attractive target for chemoprevention, and several naturally derived compounds may induce cyclin D1 degradation in cancer cells." (PMID 23710216, 2013).
cancer (continued). "Therefore, we examined whether cyclin D1 effects on cellular structure and actin organization contribute to TGFβ-mediated cancer cell migration." (PMID 23786849, 2013). "The results of FCM also showed that treatment with curcumin and HC resulted in G1 arrest of cancer cells, and the decreased expression of cyclin D1 and c-Myc by Western blotting might account for proliferation inhibition and cell cycle arrest of the treated cells." (PMID 22179587, 2012). "Interestingly, other studies have also observed this same contradiction, and in fact, have noted a distinct inverse relationship between cyclin D1 and p16 levels with poorer clinical outcome, a more aggressive cancer phenotype, and resistance to multiple chemotherapeutic agents." (PMID 22616718, 2012). "cyclin D1 may play a leading role in mediating invasion and metastasis of cancer cells." (PMID 20704822, 2010). "Besides gene amplification, cytoplasmic sequestration may also serve to regulate cyclin D1 activity in mammalian cancer cells." (PMID 21176227, 2010). "Therefore, suppression of cyclin D1 is a relevant target to combat cancer." (PMID 20424615, 2010). "However, additional studies are needed to know whether the rhythmic expression of CCND1 is deregulated in cancer." (PMID 20353609, 2010). "Additionally, several naturally derived compounds induce cyclin D1 degradation in cancer cells." (PMID 17407548, 2007). "The therapeutic ablation of cyclin D1 may be useful for the prevention and treatment of cancer." (PMID 17407548, 2007). "Thus, cyclin D1 impinges on several distinct pathways that govern cancer cell proliferation." (PMID 16863592, 2006). "Thus, FBXW8 plays an essential role in cancer cell proliferation through proteolysis of cyclin D1." (PMID 17205132, 2006). "Finally, CCND1 appears to be an outstanding candidate therapeutic target, and several studies have shown that antisense to CCND1 inhibits the growth and reverses the transformed phenotype of human cancer cells." (PMID 11870541, 2002). "This overexpression of NCOA1 in MCF-7 cells resulted in heightened expression of Cyclin D1 and VEGF, two established target genes regulated by STAT3 in several cancer types." (PMID 41562922, 2026). "The carcinoma population had a very high TFx (0.96), with 34 sCNA and regions containing FGFR1, CCND1, GNAS, and BRAF the most amplified." (PMID 41144934, 2026). "We examined the expression levels of cyclin B, Cdk1, cyclin D1, PCNA, JAK1, STAT3, and other cancer pathway components." (PMID 40350446, 2025). "Overall, this resulted in the downregulation of Wnt target genes such as cyclin D1 and c-Myc and a decrease in TCF-driven luciferase TopFlash and subsequent inhibition of cancer cell growth." (PMID 40427472, 2025). "For cell cycle regulation and cancer, the genes CCND1 and E2F7 (cell cycle regulation) and BRCA2, NF2, BRCA1, and NF1 (cancer) were found to be upregulated relative to humans." (PMID 40149424, 2025). "miR-16-1 and miR-16-2 have the same sequence and exert similar biological effects and target CCND1, CCND3, and CCNE1 and affect cancer proliferation and survival." (PMID 40061926, 2025). "They promote G0/G1 phase cell cycle arrest by upregulating p27Kip1 and p21 while downregulating cyclin D1 and cyclin‐dependent kinase 2/4 (CDK2/CDK4), thereby preventing cancer cell proliferation." (PMID 40387523, 2025). "miR-34a-5p targets many signaling molecules such as BCL2, CCND1, and SIRT1 that have a key role in the biological activities of cancer cells." (PMID 40061926, 2025). "This is interesting because Cyclin D1 is a downstream target gene of Kruppel‐like factor 5 (KLF5), which is up‐regulated in cancer due to Wnt signaling in an 8‐catenin‐dependent way." (PMID 41179371, 2025). "Genes like HRAS, CCND1, and CDKN2A are well-known drivers of cancer-related processes, including cell cycle progression, and apoptosis." (PMID 40333905, 2025).
cancer (continued). "The downstream targets of STAT3 include anti-apoptotic genes (BCL-2, BCL-XL, MCL-1), cell survival pathway genes (Cyclin-D1, Survivin), drug efflux (MDR1), and maintenance genes of cancer stem cells (CD133)." (PMID 40149331, 2025). "Genes encoding proteins such as cyclin-dependent kinase 2 (CDK2), cyclin-dependent kinase 4 (CDK4), CDC28 protein kinase 1B (CKS1B), cyclin A2 (CCNA2), and cyclin D1 (CCND1) play key roles in promoting cell division and cancer progression." (PMID 41003013, 2025). "NF-κB regulates genes involved in cell proliferation (Cyclin D1), anti-apoptosis (e.g., survivin and the inhibitor of apoptosis protein), anti-cancer drug resistance (MDR1), cancer metastasis (e.g., COX-2 and MMP9), and immunomodulation." (PMID 40599807, 2025). "Oncrasin-72 exerts its activity by inhibiting C-terminal domain phosphorylation of RNA polymerase II in sensitive human cancer cells, thereby activating JNK, suppressing JAK2/STAT3 phosphorylation, and reducing cyclin D1 expression." (PMID 40867324, 2025). "To date, the role of Ccnd1 in abnormal glucose and lipid metabolism‐associated liver senescence has been poorly investigated; however, considerable evidence suggests that Ccnd1 is essential for cancer cells to remain in the proliferative and nonsenescence stages." (PMID 39792613, 2025). "A co‐immunoprecipitation assay demonstrated a physical interaction between CCND1 and GABRD in AGS cells, confirming their cooperative role in cancer progression." (PMID 40145254, 2025). "It contributes to cancer cell proliferation by assisting in the folding of Cyclin D1 and supporting the formation of the Cyclin D1/CDK4 holoenzyme complex, which triggers cancer cell proliferation." (PMID 40214463, 2025). "Most of CEDGs like CCND1, ALDH3B1, MYEOV were frequently hypomethylated in cancer, while FGF3, FGF4, MRGPRF and CPT1A were hypermethylated in most cancers." (PMID 40478912, 2025). "In these cells, UA induces apoptosis, arrests the cell cycle, and inhibits cancer cell proliferation by downregulating key proteins such as STAT3, EGFR, and cyclin D1." (PMID 40141751, 2025). "Results included known cancer driver genes on eccDNA were identified, such as MYC, EGFR, CCND1 and MDM2." (PMID 40478912, 2025). "Other cancer genes detected in focal CNV peaks included EGFR (7p11.2 amplification), MDM2 (12q15 amplification), CCND1 (11q13.3 amplification), and MLLT10 (10p12.31 amplification), which were also enriched in TETs." (PMID 41388389, 2025). "Gene expression studies were performed to assess the impact of AgNPs on cancer-related genes such as VEGF and CYCLIN-D1." (PMID 39757333, 2025). "KITENIN expression is associated with MAPK signaling and the AP-1 axis, and knockdown of KITENIN downregulates markers of cyclin D1, COX2, MMP3 and ERK1/2, HIF-1A, EMT, stemness and aerobic glycolysis, suppressing cancer progression." (PMID 39030594, 2024). "In cancer cells, the CDK4/6–cyclin D1-Rb1-E2F axis is regarded as the most dysregulated cell cycle pathway." (PMID 38473336, 2024). "This inhibition has been linked to the downregulation of several pro-oncogenic genes, including Bcl2, survivin, cyclin D1, VEGF, and FASN, in various in vitro and in vivo cancer studies." (PMID 39267853, 2024). "It has been shown that ERK1/2 positively regulates both proliferation-related (e.g. c-Myc, Cyclin D1) and migration-related (e.g. matrix metalloproteinase-2; MMP2) proteins to drive cancer cell progression." (PMID 38311733, 2024). "PN treatment inhibited cancer cell growth by inhibiting STAT3-mediated production of Bax, Bcl-2, Bcl-xL, and cyclin D1." (PMID 38397437, 2024). "The molecular mechanismsof cancer pathway genes were deactivated,including COX, GJA1, CD44, FGF9, and CCND1." (PMID 38481680, 2024).
cancer (continued). "In particular, it was shown that PARP14 increases cyclin D1 levels, involved in G1/S transition both in normal and cancer cells, by binding to the 3′ UTR of cyclin D1 mRNA, stabilizing the transcript." (PMID 39189367, 2024). "We identified recognized cancer driver genes (EGFR, MTOR, CCND1, and MYC) within Epi_C1_SPARC and Epi_C6_TCIM subclusters, observing high variability of CNVs in cell proliferation-related genes (TOP2A, MKI67)." (PMID 38720887, 2024). "Indeed, subcellular localization of Cyclin D1 outside the nucleus has been reported to correlate with a lower proliferative index in different cancer types, this suggesting that the restriction of Cyclin D1 to the perinuclear region may allow the suppression of cell cycle progression." (PMID 38977944, 2024). "The results revealed that DD-9 can effectively reduce the mRNA expression of β-catenin and its target genes cyclin D1 and LEF1 and inhibit their transcription level, compared to that in the control group in tested cancer cells." (PMID 38921589, 2024). "Cyclin D1 is an important cell cycle regulatory protein responsible for activating CDK4 and CDK6 kinase activities and promoting cancer cell proliferation." (PMID 39768127, 2024). "As a positive control to our analysis, the APAtrap analysis was extended to the cyclin D1 (CCND1) mRNA, also known to have an increased SLR in cancer." (PMID 39527514, 2024). "Activated STAT3 signaling is known to regulate essential cancer cell mechanisms such as proliferation, survival, and metastasis pathways by modulating genes involved in cell proliferation (PCNA), the cell cycle (Cyclin D1), and apoptosis (PARP and Caspase 3)." (PMID 39273033, 2024). "For example, APOE, PLAU, CDK1 and MUC1 were significantly higher in TNBC tissues than in cancer-parasite tissues, whereas PDGFRB, RET, ROCK2, CCND1 and PPARA were significantly lower in TNBC tissues than in cancer-parasite tissues." (PMID 38329441, 2024). "While low-dose ISO treatment effectively induces G0/G1 growth arrest by suppressing the key cell cycle regulatory protein cyclin D1 expression, high-dose ISO triggers an apoptotic response of cancer cells by inhibiting anti-apoptotic XIAP gene transcription." (PMID 38339062, 2024). "Erik’s report illustrate the complex nature of cancer cell cycles, genes (CDK4, CDK6, CCND1, CDK2, and CCNE1) that regulate the G1/S transition yield particularly variant vulnerabilities in different cancer cell." (PMID 38582921, 2024). "Studies have reported that the downregulation of the Cyclin D1/CDK4-Rb pathway suppresses cell proliferation and promotes apoptosis of cancer cells." (PMID 39161904, 2024). "It induced cell cycle arrest at the G0/G1 and G2/M phases by activating P21, P27, Bax, cyclin E, and decreasing cyclin D1 consequently downregulating cyclin-dependent kinases such as CDK1,CDK2,CDK4, and CDK6 in various cancer cell lines." (PMID 39267853, 2024). "At high doses, PI-103 treatment induced cancer cell apoptosis as observed by cleaved PARP and cell cycle inhibition with cyclin D1 suppression." (PMID 40115434, 2024). "CCND1, located on chromosome 11q13, is a member of the CCND family and is commonly used as a marker for cell proliferation and cancer." (PMID 38787178, 2024). "Overexpression of cyclin D1 (CCND1) and C-MYC are frequently observed in various cancers which lead to the aberrant cell cycle and cell proliferation." (PMID 39582977, 2024). "The cell cycle analysis and down-regulation of Cyclin D1 (CCND1) and cyclin dependent kinase 4 (CDK4) revealed that cancer cells were arrested in the sub-G1 phase." (PMID 36828883, 2023).